DRD2 (dopamine receptor D2)
Diseases named in the same sentence as DRD2 in open-access papers (continued):
Sharing a sentence is not in itself a finding about the gene and the disease.
Ovarian Tumors (3 papers, 2021 to 2025). "The significant finding of this study was that ONC201 reduced the expression of DRD2, and inhibited ovarian tumor growth and reduced the ability of invasion via activation of ClpP induced oxidative stress pathways and inactivation of P13K/AKT/mTOR and MAPK pathways." (PMID 35372029, 2022).
prostate carcinoma (3 papers, 2018 to 2021). A carcinoma that arises from epithelial cells of the prostate gland. "We have included in this study a new methylated assay of DRD2 promoter region, which showed hypermethylation in prostate cancer cells compared to benign primary epithelial cells." (PMID 30204798, 2018). "However, downregulation of DRD2 by trifluoperazine and haloperidol also results in decreased invasion and migration in prostate cancer cells, indicating the functional diversity of DRD2 and its downstream targets in different types of cancer." (PMID 33557912, 2021). "Interestingly, a phase I study with the DRD2 antagonist ONC201, demonstrated some clinical benefit in five endometrial and prostate cancer patients from a group of 27 advanced cancer patients." (PMID 31478179, 2020).
Sleep Dysfunction (3 papers, 2020 to 2025). "Further prospective studies in a larger sample size from other populations and ethnic groups would help clarify the role of the DRD2 genotypes in the regulation of the association between job stress and sleep dysfunction." (PMID 33167416, 2020). "Participants were divided into high or low JS groups and A1A1 or A1A2/A2A2 genotype to investigate the interaction between DRD2 polymorphism and JS concerning sleep dysfunction." (PMID 33167416, 2020). "Furthermore, we found that people with both the A1 allele of the DRD2 gene and JS were more likely to have sleep dysfunction." (PMID 33167416, 2020). "Recent studies have shown that incessant job stress could eventually result in sleep dysfunction (SD), and most importantly, the essential role dopamine receptor D2 (DRD2) gene polymorphisms play in the psychopathological mechanism of SD." (PMID 33167416, 2020). "For the sleep dysfunction total score, the model summary was significant R2 = 0.111, F = 10.703, p < 0.001 and the interaction of between stress and DRD2 rs1800497 genotype was significant, with a R2 change of 0.007 (F = 5.661, p = 0.018)." (PMID 33167416, 2020). "In summary, our results showed a remarkable relationship between the DRD2 genotype and JS concerning sleep dysfunction among the Chinese Han population." (PMID 33167416, 2020).
adenomyosis (2 papers, 2021 to 2022). The growth of endometrial tissue inside the muscular wall of the uterine corpus. "In addition, aged female mice deficient in DRD2 developed uterine adenomyosis spontaneously in response to prolonged PRL exposure." (PMID 35330066, 2022). "DRD2 agonists have been shown to suppress PRL-induced adenomyosis and also have therapeutic potential for reducing pain and treating adenomyosis, likely through the promotion of the long isoform of PRLR (PRLR-L) and the inhibition of angiogenesis by DRD2." (PMID 35330066, 2022).
Arthritis (2 papers, 2015 to 2023). Inflammation of a joint. "Importantly, Drd2-knockout mice manifested more severe inflammation of limbs as determined by the increased clinical arthritis score, ankle joint width, and hind paw thickness, as well as higher serum anti-CII IgG level than wild-type mice." (PMID 26693483, 2015). "Unlike Drd2−/− CIA mice, Drd1-null CIA mice did not manifest either more severe inflammation of limbs as determined by clinical arthritis score, ankle joint width, and hind paw thickness or higher serum anti-CII IgG level, in comparison with wild-type CIA mice." (PMID 26693483, 2015).
brain tumors (2 papers, 2021 to 2024). "Interestingly, DRD2 is overexpressed in GB and in midline brain tumors: a DRD2 blockade is sufficient to inactivate growth factor signaling and induce apoptosis; thus, these tumors have enhanced sensitivity to DRD2 antagonists." (PMID 39767637, 2024).
cardiac arrhythmia (2 papers, 2021 to 2024). Any disturbances of the normal rhythmic beating of the heart or MYOCARDIAL CONTRACTION. "Additionally, thioridazine and other DRD2 antagonists could be modified to improve tolerability, as dose-limiting toxicities such as cardiac arrhythmias and neurologic events have been reported in patients given thioridazine for AML treatment." (PMID 33922599, 2021).
coronary artery disease (2 papers, 2014 to 2020). "A study on Czech patients with coronary heart disease found that the DRD2 polymorphism (rs1800497) was significantly associated with failure to cease smoking." (PMID 33287325, 2020).
corticotroph adenomas (2 papers, 2018 to 2020). "There was no statistical difference in SSRs and dopamine receptor type 2 (DRD2) gene expression between functioning and silent corticotroph adenomas." (PMID 33066652, 2020).
esophageal squamous cell carcinoma (2 papers, 2020 to 2024). Esophageal squamous cell carcinoma (ESCC) is a type of esophageal carcinoma (EC) that can affect any part of the esophagus, but is usually located in the upper or middle third. "Thioridazine (THD), an antagonist of the dopamine receptor D2, is a potent anti-anxiety and anti-psychotic that in combination with radiotherapy promotes G0/G1 phase cell cycle arrest by CDK4 and cyclinD1 downregulation on the esophageal squamous cell carcinoma (ESCC) ECA-109 and TE-1 cell lines." (PMID 32923398, 2020).
hippocampal atrophy (2 papers, 2022 to 2023). "This study suggests that DRD2 Taq1A polymorphism moderates the association between PTSD symptomatology and left CA3 volume, which promotes an etiological understanding of the hippocampal atrophy at the subfield level." (PMID 34086098, 2022).
morphine dependence (2 papers, 2022 to 2023). Strong dependence, both physiological and emotional, upon morphine. "Our observations regarding drd2a elevation in long-term morphine treated and morphine withdrawn larvae further support the previous finding regarding the association of increased drd2 to morphine dependence and withdrawal." (PMID 36835497, 2023).
myoclonus dystonia (2 papers, 2021 to 2025). "DRD2 has been linked to psychiatric problems in myoclonus dystonia." (PMID 33200438, 2021).
osteosarcoma (2 papers, 2020 to 2024). A usually aggressive malignant bone-forming mesenchymal neoplasm, predominantly affecting adolescents and young adults. "Reports state that DRD2 on the cell membrane can inhibit tumor growth by downregulating eEF1A2, whereas eEF1A2 increases osteosarcoma progression and degradation by triggering the Akt/mTOR signaling pathway, highlighting DRD2's anti-osteosarcoma effects." (PMID 38586328, 2024).
somatotropinomas (2 papers, 2014 to 2020). "Moreover, a latest study positively correlated FLNA and DRD2 expression in somatotropinomas, in line with our previous report in MMQ cell line." (PMID 33664708, 2020).
substance-related disorder (2 papers, 2013 to 2017). A category of psychiatric disorders which include disorders related to the taking of a drug of abuse (including alcohol, prescribed medications and recreational drugs). "Unlike the widely studied TaqIA, there are only a few association studies with the TaqIB SNP, located in intron 1 of the DRD2 gene and substance-related disorders." (PMID 23840506, 2013).
AIDS (1 paper, 2014). A syndrome resulting from the acquired deficiency of cellular immunity caused by the human immunodeficiency virus (HIV). "Recently, decreased levels of the preproenkephalin mRNA (PENK) and dopamine receptor D2 (DRD2) in the dorsolateral prefrontal cortex (DLFPC) in postmortem brain of subjects with HIV/AIDS has been reported." (PMID 24405578, 2014).
asthenia (1 paper, 2023). Clinical sign or symptom manifested as debility, or lack or loss of strength and energy. "The incidence of akathisia was higher in DRD3 rs6280 Ser/Ser homozygotes vs. Gly allele carriers and asthenia appeared more often in DRD2 rs1799732 G/- subjects vs. G/G homozygotes." (PMID 36873203, 2023).
atopic dermatitis (1 paper, 2020). "While we were screening a molecular target for dermatitis using meta-analysis, we found the expression levels of dopamine receptor D2 were increased from datasets of atopic dermatitis patients (GSE6012, and GSE120721." (PMID 32375285, 2020).
Atrophy (1 paper, 2024). Any weakening or degeneration, especially through lack of use. "If the level of DRD1 and DRD2 is insufficient, motor atrophy will be caused." (PMID 40777974, 2024).
blood pressure (1 paper, 2019). "Several SNPs within the human DRD2 gene have been associated with clinically relevant conditions including elevated blood pressure and essential hypertension." (PMID 31727925, 2019).
brain infarction (1 paper, 2021). Tissue necrosis in any area of the brain, including the cerebral hemispheres, the cerebellum, and the brain stem. "Dopamine (DA)-ergic pathway function is known to be greatly impaired in the weeks following brain infarction, as shown by decreased DA availability, and both DRD2 and DAT expression." (PMID 35058756, 2021).
cerebral palsy (1 paper, 2018). A group of disorders affecting the development of movement and posture, often accompanied by disturbances of sensation, perception, cognition, and behavior. "The results indicated that there was a statistically significant association between a polygenic dopamine gene score reflecting the collective effects of five dopamine gene polymorphisms (COMT, DAT, DRD1, DRD2, and DRD3), and CIMT outcome in 33 children with spastic unilateral cerebral palsy." (PMID 29339100, 2018).
cerebral small vessel disease (1 paper, 2025). Cerebral small vessel disease is the term currently used to pathological processes that affect the brain parenchymal circulation (arterioles, capillaries, and veins). "In previous work, we have shown that cerebral small-vessel disease, and specifically, white-matter lesion burden to be associated with individual differences in striatal DRD2 availability." (PMID 39885603, 2025).
cyst (1 paper, 2020). A sac-like closed membranous structure that may be empty or contain fluid or amorphous material. "Among the downregulated genes, we noticed an expected strong decrease in the expression of dopamine receptor Drd1 and Drd2 genes in mice with high cyst burden." (PMID 31940479, 2020).
dermatitis (1 paper, 2020). An inflammatory process affecting the skin. "Here, we found the expression levels of dopamine receptor D2 is higher in skin biopsies of dermatitis patients and an oxazolone-induced animal model of dermatitis." (PMID 32375285, 2020). "We found the expression levels of dopamine receptor D2 are relatively higher in the lesion of dermatitis patients compared to control subjects and future study remains to determine which type of immune cells are responsible for the expression of dopamine receptor in the dermatitis lesion." (PMID 32375285, 2020). "Thus, infiltrated T cells into the dermatitis lesion may express dopamine receptor D2." (PMID 32375285, 2020).
developmental delay (1 paper, 2013). "It is also not known whether DRD2-TAQ-IA contributes to communicative impairments and developmental delay, and whether it contributes to the interaction between vocabulary and grammar learning." (PMID 23741438, 2013).
diabetic retinopathy (1 paper, 2025). "The DRD2_rs4936270 variant affects dopamine receptor D2 function, providing evidence for dopaminergic dysregulation in diabetic retinopathy pathogenesis." (PMID 41010507, 2025). "This study advances our understanding of diabetic retinopathy pathogenesis by identifying novel genetic variants (ABCA4_rs17110929, MMP2-AS1_rs2576531, FOXP1_rs557869288) and additional loci (MRPS33_rs1533933, DRD2_rs4936270)." (PMID 41010507, 2025).
diffuse intrinsic pontine glioma (1 paper, 2023). A neuroglial tumor that arises from the middle portion of the brain stem. "There were some preclinical data supportive of DRD2 antagonistic activity, and the clinical activity seen in diffuse intrinsic pontine gliomas (DIPG) has been suggested to be mediated through DRD2 inhibition." (PMID 37046596, 2023).
dwarfism (1 paper, 2019). "Autosomal recessive OSD caused by COL9A3 and COL9A2 mutations have previously been identified in the Labrador Retriever (dwarfism with retinal dysplasia 1—drd1) and Samoyed dog (dwarfism with retinal dysplasia 2—drd2) respectively; both of those mutations were excluded in all affected NID." (PMID 31415586, 2019). "Variants associated with OSD have been identified in COL9A3 in the Labrador Retriever and in COL9A2 in the Samoyed dog, termed drd1 and drd2 (dwarfism with retinal dysplasia 1 and 2) respectively." (PMID 31415586, 2019).
emotion dysregulation (1 paper, 2022). "The goal of this study was to explore the moderating role of a polygenic dopamine composite consisting of COMT and DRD2 in the relationship between peer victimization and externalizing problems in Chinese adolescents, as mediated by emotion dysregulation, and the potential sex differences." (PMID 36397091, 2022).
endometrial tumors (1 paper, 2021). "However, this association makes antagonism of DRD2 a compelling treatment hypothesis for both type 1 and 2 endometrial tumors." (PMID 33557912, 2021). "Using the TCGA database (N = 371 endometrial tumors), DRD2 mRNA expression was higher in serous type compared with endometrioid type EC (p = 0.02)." (PMID 33557912, 2021).
esophageal cancer (1 paper, 2021). A primary or metastatic malignant neoplasm involving the esophagus. "Previous studies suggested that dopamine receptor D2 (DRD2) expression can be used to evaluate the prognosis of patients with gastric or esophageal cancer." (PMID 34646329, 2021).
fibroid tumor (1 paper, 2021). "However, expression of CHRM2 is co-regulated with the expression of DRD2 in healthy myometrium but not in fibroid tumors, where correlation between these two genes has not been observed." (PMID 34440356, 2021).
hypercortisolemia (1 paper, 2017). "Such hypercortisolemia alters dopamine binding and DRD2 availability in the striatum, which might underlie the changes in hedonic reactivity." (PMID 29141007, 2017).
lung adenocarcinoma (1 paper, 2022). A carcinoma that arises from the lung and is characterized by the presence of malignant glandular epithelial cells. "Nonetheless, a plausible role of nicotine or nAChRs in peripheral dopamine synthesis may not be ruled out, especially since correlative analyses from our data as well as TCGA database showed positive correlation between some of the nAChRs and DRD2 in lung adenocarcinoma patients." (PMID 36072788, 2022).
lymphoid cancer (1 paper, 2024). "While cell lines from certain tissues seem to be equally inhibited by top GPCR drugs (e.g., lung), others are sensitive to specific GPCR drugs, such as lymphoid cancer cells, which are particularly inhibited by DRD2, CHRM1, CHRM2, HTR1A, and HTR2A antagonists." (PMID 38723607, 2024).
multiple sclerosis (1 paper, 2023). A progressive autoimmune disorder affecting the central nervous system resulting in demyelination. "This notion is consistent with our recent study that inactivation of astrocytic dopamine D2 receptor (Drd2)-6-pyruvoyl-tetrahydropterin synthase (PTS) axis is able to diminish astrogliosis and neurodegeneration in a mouse model of multiple sclerosis." (PMID 37674228, 2023).
neuropathy (1 paper, 2023). A disorder affecting the nervous system that manifests with pain, tingling, numbness, and/or muscle weakness. "We analyzed genes known to be targeted by cannabigerol and other cannabinoids, including Cnr1, Cnr2, Gpr55, Faah, Mgll, Adra2a-c, Pparg, or to have been previously published as volatile in a cisplatin-induced neuropathy setting in DRG, including Drd2, Gfap, and Oprm1." (PMID 37895913, 2023).
pancreatitis (1 paper, 2022). Inflammation of the pancreas. "Similarly, we found that DRD2 activation with quinpirole downregulated the expression of CTSB in NaT-induced pancreatitis." (PMID 35927992, 2022).
Retinal dysplasia (1 paper, 2022). Abnormal growth and differentiation, structure and appearance of the retina present from birth. "It would be of interest to examine whether canine SLC4A5 or other known regulators of RPE fluid flow are altered in drd1 and drd2 canines exhibiting retinal dysplasia." (PMID 35216333, 2022).
Sepsis (1 paper, 2025). Sepsis is defined as life-threatening organ dysfunction caused by a dysregulated host response to infection. "Pramipexole, a DRD2 agonist, conferred a significant protection in mouse models of endotoxemia and polymicrobial sepsis." (PMID 40703506, 2025). "However, larger and well-controlled clinical trials are needed to evaluate the efficacy and safety of DRD2 agonists, like pramipexole, in diverse sepsis patient populations, considering factors like sepsis stage, infection source, and comorbidities." (PMID 40703506, 2025).
serous carcinoma (1 paper, 2021). "DRD2 expression was analyzed by immunohistochemistry in human endometrioid and serous carcinoma specimens." (PMID 33557912, 2021).
synucleinopathy (1 paper, 2024). A neurodegenerative disease that is characterized by the abnormal accumulation of aggregates of alpha-synuclein protein in neurons, nerve fibers or glial cells. "In the present analysis, both Drd2 and Rgs8 transcripts decrease in early synucleinopathy." (PMID 38172128, 2024).
thyroid tumor (1 paper, 2021). A benign or malignant neoplasm affecting the thyroid gland. "More important, elevated DRD2 expression was associated with a survival disadvantage for patients with kidney, endometrial, urothelial, and thyroid tumors." (PMID 33665638, 2021).
uveitis (1 paper, 2021). An inflammatory process affecting a part of or the entire uvea. "The importance of the dopaminergic system has also been shown in endotoxin-induced uveitis, in which a mixed DRD2 agonist/DRD1 antagonist was able to reduce immune-cell infiltrates in the eye." (PMID 35008877, 2021).